OAS1 (2'-5'-oligoadenylate synthetase 1)
Diseases named in the same sentence as OAS1 in open-access papers (continued):
Sharing a sentence is not in itself a finding about the gene and the disease.
bladder cancer (10 papers, 2020 to 2025). "We knocked down OAS1 using technology to assess its effects on bladder cancer, specifically its influence on the proliferation, migration, and invasion abilities of bladder cancer cell lines (T24 cells)." (PMID 41584451, 2025). "OAS1 values were significantly lower in normal bladder epithelial cells than in bladder cancer cells." (PMID 36468020, 2022). "Therefore, the primary objective of this study is to leverage TPECs-related genes, with a specific focus on OAS1, to construct a novel prognostic model for bladder cancer." (PMID 41584451, 2025). "In the present study, we constructed a novel and highly reliable four-gene marker (OAS1, AOC2, HOXB5, and HSH2D) for predicting the prognosis of bladder cancer based on TPECs-related genes." (PMID 41584451, 2025). "The high expression of ABCB9, SPTBN2, GULP1, IGF1, P4HB, NES and DPYSL2 and the low expression of ANXA6, OAS1, RAD9a, DNASE2B and FANCF would be beneficial to the prognosis of bladder cancer patients." (PMID 37845668, 2023). "After performing a series of bioinformatic and machine learning approaches, we identified distinct tumor microenvironment clusters and three bladder cancer specific immune-related genes (EGFR, OAS1 and MST1R)." (PMID 36267410, 2022). "To test the study hypothesis, in human bladder epithelial cells, we detected the expression of FBXO6, OAS1, and TMEM229B genes, as well as three different bladder cancer cell lines by using RT-qPCR technique." (PMID 36468020, 2022). "OAS1 induced by interferons is reported to be one gene in prognostic signature for patients with bladder cancer, despite a lack of sufficient experimental studies." (PMID 33428606, 2021).
pancreatic cancer (10 papers, 2021 to 2025). "Previous studies have reported the predictive value of a risk score constructed by combining OAS1 with 20 other prognostic genes in pancreatic cancer, and ROC evaluation showed good predictive value (AUC=0.833)." (PMID 35898870, 2022). "Compared with normal pancreatic tissue, OAS1 is highly expressed in pancreatic cancer tissue, and high expression of OAS1 is associated with a low overall survival rate.OAS1 may be involved in Trastuzumab-resistant gastric cancer." (PMID 41584451, 2025). "Our study revealed that OAS1 is highly expressed in tumor tissues compared to normal tissues and is associated with the prognosis of patients with various types of tumors, including pancreatic cancer." (PMID 37928544, 2023). "A previous study proved that OAS1 was associated with poor prognosis in pancreatic cancer." (PMID 36969077, 2023). "In conclusion, the high expression of OAS1 is associated with poor prognosis of pancreatic cancer." (PMID 35898870, 2022). "The results indicated a significantly higher expression of OAS1 in pancreatic cancer tissues compared to adjacent normal tissues." (PMID 37928544, 2023). "It is worth noting that in the GSE28735 dataset, we analyzed the expression levels of OAS1 in pancreatic cancer tissues and adjacent normal tissues from 45 patients." (PMID 37928544, 2023). "Based on the expression of OAS1 and pathological staging, we developed a survival prediction model for pancreatic cancer patients using the Cox model and visualized it using Nomogram plots." (PMID 37928544, 2023). "Our study demonstrated that knockdown of OAS1 in pancreatic cancer cell lines significantly reduced their invasive ability and increased their apoptosis rate." (PMID 37928544, 2023). "Subsequently, To investigate the implication of OAS1 in tumor cell progression, we performed the knock-down test using siRNAs in two pancreatic cancer cell lines." (PMID 37928544, 2023). "Our results demonstrated that in both Bxpc-3 (siRNC: 402 ± 3.05, siRNA3: 145± 11.67) and Panc-1 (siRNC: 450 ± 6.51, siRNA3: 140± 1.00) cell lines, the invasion ability of pancreatic cancer cells was significantly reduced after OAS1 knockdown." (PMID 37928544, 2023). "We conducted a comprehensive investigation into the correlation between OAS1 expression and the immune microenvironment in pancreatic cancer." (PMID 37928544, 2023). "Samples are grouped according to the median value of OAS1 and then to study the correlation between the expression of OAS1 and the prognosis of patients with pancreatic cancer." (PMID 35898870, 2022). "Kaplan-Meier survival curves and univariate analysis were applied, the survival time of pancreatic cancer patients with high OAS1 expression was shorter than that of patients with low OAS1 expression." (PMID 35898870, 2022). "OASL, as the most significant positive correlation with the expression of OAS1, was conformed that the high expression of OASL was also associated with poor OS in pancreatic cancer." (PMID 35898870, 2022). "Results derived from these three databases all indicated that elevated levels of OAS1, OAS2, OAS3, and OASL were associated with poor overall survival (OS) in pancreatic cancer." (PMID 35719943, 2022). "OAS1 expression was divided into high and low groups, and it was mainly expressed in the cytoplasm of pancreatic cancer cells." (PMID 35898870, 2022). "To explore the potential molecular function of OAS1 in pancreatic cancer, we conducted GSEA between low and high expression samples to predict OAS1-related signaling pathways." (PMID 35898870, 2022). "Results revealed that the positive OAS1 protein stains were weak in normal pancreatic tissues but showed medial signal intensity in pancreatic cancer tissues." (PMID 35719943, 2022). "Our study also found high expression of OAS1 in pancreatic cancer, consistent with those reports of abnormal expression of OAS1 in various cancers." (PMID 35898870, 2022).
pancreatic cancer (continued). "We compared the protein expression of OAS1 between normal pancreatic tissue and pancreatic cancer tissue by HPA." (PMID 35898870, 2022). "In Pei Pancreas and Segara Pancreas datasets, OAS1 was overexpressed with a fold change respectively of 5.442 and 2.241 in pancreatic carcinoma compared with the normal tissues." (PMID 35719943, 2022). "Among 21 genes from the immune-related signature, MET, OAS1, and OASL were significantly associated with prognosis of pancreatic cancer patients." (PMID 33869254, 2021). "MET, OAS1, and OASL mRNAs were all up-regulated in pancreatic cancer and associated with unfavorable prognosis." (PMID 33869254, 2021). "Higher OAS1 expression was detected in pancreatic cancer than para-carcinoma tissues in the GSE15471 (p = 3.519e-07) and GSE62452 datasets (p = 1.215e-11)." (PMID 33869254, 2021). "Among them, MET, OAS1, and OASL were verified to be markedly up-regulated in pancreatic cancer and associated with poor clinical outcomes of patients." (PMID 33869254, 2021). "Among these genes, MET, OAS1, and OASL were validated to be up-regulated in pancreatic cancer and associated with unfavorable prognosis of patients." (PMID 33869254, 2021). "Furthermore, AUC plots showed that the expression of OAS1 in patients with pancreatic cancer can predict overall survival at 1 year (AUC=0.646), 2 years (AUC=0.723) or 3 years (AUC=0.734)." (PMID 37928544, 2023). "We aimed to further explore the role played by OAS1 in pancreatic cancer development." (PMID 37928544, 2023). "Finally, the roles of the OAS1 on apoptosis, migration and invasion were investigated in two pancreatic cancer cells." (PMID 37928544, 2023). "In conclusion, our findings suggest that OAS1 could be a potential biomarker for pancreatic cancer prognosis and a target for therapeutic intervention." (PMID 37928544, 2023). "In addition, we further analyzed the expression level of OAS1 in pancreatic cancer tissue using GEO data (GSE15471), and found that OAS1 mRNA in tumors was also significantly higher than that in normal tissue (p<0.001)." (PMID 35898870, 2022). "The aim was to explore the prognostic value of OAS1 in pancreatic cancer." (PMID 35898870, 2022). "Immunohistochemical staining also indicated OAS1 was upregulated in pancreatic cancer tissue." (PMID 35898870, 2022). "Furthermore, Kaplan-Meier survival curves showed that the high expression of OAS1 was related to the poor OS (p=0.020) in patients with pancreatic cancer." (PMID 35898870, 2022). "In this study, OAS1 mRNA was significantly upregulated in patients with pancreatic cancer." (PMID 35898870, 2022). "Moreover, Kaplan-Meier survival curves showed that the prognostic value of OAS1 in pancreatic cancer." (PMID 35898870, 2022). "OAS1 expression in pancreatic cancer has been confirmed by many studies." (PMID 35898870, 2022). "In addition, we explored the relationship between OAS1 and immune checkpoints by analyzing multiple pancreatic cancer bulk transcriptome datasets (GSE71729, GSE21501, ICGC_array, E_MTAB_6134, ICGC_CA_seq, GSE79668, GSE62452, GSE78229, GSE28735, TCGA_PAAD, GSE57495)." (PMID 37928544, 2023). "In addition, it was found that OAS1 may play a key role in the immune infiltration of pancreatic cancer." (PMID 35898870, 2022). "This further speculates that OAS1 is related to the prognosis of pancreatic cancer." (PMID 35898870, 2022). "We speculate that OAS1 may be involved in the development of pancreatic cancer." (PMID 35898870, 2022). "Therefore, we could speculate that OAS1 can be an important biomarker for poor prognosis of pancreatic cancer." (PMID 35898870, 2022). "Therefore, this study suggests that OAS1 may serve as a new prognostic biomarker for pancreatic cancer." (PMID 35898870, 2022). "Whether OAS1 can be used as a prognostic indicator of pancreatic cancer is worth exploring." (PMID 35898870, 2022).
pancreatic cancer (continued). "Some of them (ITGA3, CDK1, IFIT3, ANXA1, ANXA2, OAS1, and LACTB) have been studied to varying degrees concerning their relationship with pancreatic cancer." (PMID 36834681, 2023). "Western blotting results showed that the protein expression levels of OAS1, OAS2, OAS3, and OASL were significantly elevated in pancreatic cancer cells compared with normal pancreatic cells." (PMID 35719943, 2022). "Hence, OAS1 could be a biomarker for poor prognosis of patients with pancreatic cancer." (PMID 35898870, 2022). "The potential prognosis values of OAS1, OAS2, OAS3, and OASL in pancreatic cancer were investigated using Kaplan-Meier Plotter, GEPIA, and OncoLnc databases." (PMID 35719943, 2022). "We further analyzed the mRNA levels of OAS1, OAS2, OAS3, and OASL in pancreatic cancer tissues and normal pancreatic tissues based on Oncomine and GEPIA databases." (PMID 35719943, 2022). "Immunohistochemical stains of OAS1, OAS2, OAS3 and OASL proteins in human pancreatic cancer tissues and normal pancreatic tissues were searched from the HPA database." (PMID 35719943, 2022). "The co-expressed genes that related to OAS1, OAS2, OAS3, and OASL were respectively identified in Pei Pancreas dataset of Oncomine database with 16 normal pancreatic tissues and 36 pancreatic carcinoma tissues." (PMID 35719943, 2022). "The expression of MET, OAS1, and OASL in pancreatic cancer was verified in the GSE15471 and GSE62452 datasets." (PMID 33869254, 2021). "We identified three key genes (MET, OAS1, and OASL) that were all up-regulated in pancreatic cancer and indicated an unfavorable prognosis." (PMID 33869254, 2021). "In addition, by analyzing the GEPIA database, the mRNA levels of OAS1, OAS2, OAS3, and OASL were all significantly higher in pancreatic cancer tissues than normal pancreatic tissues." (PMID 35719943, 2022). "Second, the mechanism of OAS1 in the development of pancreatic cancer was not explored in this study." (PMID 35898870, 2022). "Collectively, we identified three immune-related prognostic genes MET, OAS1, and OASL, which could be promising therapeutic targets as well as prognostic markers for pancreatic cancer." (PMID 33869254, 2021). "OAS1 was highly expressed in pancreatic cancer compared with normal pancreatic tissue." (PMID 35898870, 2022). "Then we compared OAS1 mRNA expression in 179 pancreatic cancer tissues and 171 normal tissues." (PMID 35898870, 2022). "However, the prognostic value of OAS1 in pancreatic cancer has not been studied." (PMID 35898870, 2022). "However, the relationship between OAS1 and pancreatic cancer has not been clarified." (PMID 35898870, 2022). "However, the prognostic value and mechanism of OAS1 in pancreatic cancer have not been analyzed." (PMID 35898870, 2022). "Thus, MET, OAS1, and OASL could be potential therapeutic markers in pancreatic cancer." (PMID 33869254, 2021).
HIV-1 infection (8 papers, 2010 to 2025). The type species of lentivirus and the etiologic agent of acquired immunodeficiency syndrome (AIDS). "HIV-1 infection of pericytes significantly upregulated expression of all OAS genes at the mRNA level but selectively OAS1, OAS2 and OAS3 at the protein level." (PMID 36778388, 2023). "Among genes under differential expression during HIV-1 infection, several showed evidence for cis-regulation but only one, involving the interferon stimulated OAS1, reached study-wide significance." (PMID 20195503, 2010). "Furthermore, sustained upregulation of this ISG cluster, including ISG15, MX1, OAS1 and STAT1, is a hallmark of untreated HIV-1 infection." (PMID 41226717, 2025). "They found that persistent HIV-1 infection in humanized-mice led to induction of IFNs and ISGs including MX2, IFITM3, Trim22, ISG15, OAS1, and IFN regulatory factor 7 (IRF7) both in peripheral blood mononuclear cells (PBMCs) and in the spleen." (PMID 30665429, 2019). "Most interestingly, silencing of OAS1, OAS2, OAS3, or OASL markedly increased HIV-1 replication in human brain pericytes, providing the first evidence that the OAS family can regulate HIV-1 infection in human pericytes." (PMID 37209263, 2023). "We also noted that HIV-1 infection induces a prominent antiviral state in early/mid-gestation HCs, characterized by transcription and secretion of IFN-α and significantly elevated transcription of the RLRs, STAT1, STAT5, ISG15, OAS1, IFIT1, IFIT2, IFIT3, and Viperin." (PMID 34432853, 2021).
prostate carcinoma (8 papers, 2012 to 2023). A carcinoma that arises from epithelial cells of the prostate gland. "Study shows that the OAS1 SNP polymorphism is significantly associated with the risk of prostate cancer." (PMID 37746262, 2023). "The OAS1 rs2660 AA genotype increases the risk of prostate cancer, whereas the GG genotype has a protective effect on prostate cancer." (PMID 37746262, 2023). "Only one study of the association between prostate cancer and OAS1 was done on a smaller sample size and 3 SNPs different from our selection where an association with rs2660 was found." (PMID 23272139, 2012). "Moreover, overexpression of OAS1 in myeloid malignancies has been found to increase genomic instability, while polymorphism of the OAS1 gene, such as OAS1rs2660, is associated with increased susceptibility to prostate cancer." (PMID 37928544, 2023). "The expression of OAS1 was negatively correlated with breast and prostate cancer progression, whereas it was positively correlated with prognosis in patients with colorectal cancer." (PMID 39132059, 2022). "Within those sub-pathways, 5 genes (TLR1, TLR6, OAS1, OAS2, and COX-2) were nominally associated with advanced prostate cancer risk." (PMID 23272139, 2012). "Polymorphisms in OAS1 have been shown to be associated with advanced prostate cancer although the molecular mechanism has not been elucidated." (PMID 37686559, 2023). "Two sub-pathways (intracellular antiviral molecules and extracellular pattern recognition) and four genes in these sub-pathways (TLR1, TLR6, OAS1, and OAS2) were nominally associated with advanced prostate cancer risk and harbor several SNPs nominally associated with advanced prostate cancer risk." (PMID 23272139, 2012). "rs1131454 (OAS-1; G > A) is involved in enterovirus, coronary atherosclerosis, tuberculosis (TB), HCV, Dengue virus, H1N1 and H5N1 influenza virus, WNV, and prostate cancer." (PMID 36833454, 2023).
melanoma (7 papers, 2010 to 2026). A malignant, usually aggressive tumor composed of atypical, neoplastic melanocytes. "Elevated expression levels of OAS1 were observed in ICB-resistant melanoma tumors from Res 499 cell, highlighting its potential role in conferring immunotherapy resistance." (PMID 37928544, 2023). "We found that OAS1 was more accurate in predicting the efficacy of the Gide2019_PD1_Melanoma cohort (AUC=0.75) compared to the standard immunotherapy prediction model." (PMID 37928544, 2023). "In this study, 7 genes (CYTL1, CCL8, FCGR2C, OAS1, HAPLN3, WIPF1, CLIC2) were identified as prognostic signatures for melanoma." (PMID 33428606, 2021). "Over-expression of SOCS proteins in melanoma cell lines led to significant inhibition of Tyr701-phosphorylated STAT1 (P-STAT1) and gene expression following stimulation with IFN-α (IFIT2, OAS-1, ISG-15) or IFN-γ (IRF1)." (PMID 20398276, 2010).
Sjögren's syndrome (7 papers, 2017 to 2023). "Furthermore, OAS1 SNPs are associated with the occurrence of several diseases, including diabetes, tuberculosis infection, Sjogren’s syndrome, central nervous system (CNS) involvement of enterovirus 71 infection and multiple sclerosis." (PMID 37746262, 2023). "Additional genetic polymorphisms reported to be associated with risk for Sjögren’s syndrome include variants of interleukin 10 (IL-10), tumor necrosis factor (TNF), antigen peptide transporter 2 (TAP2), and 2′-5′-oligoadenylate synthetase 1 (OAS1)." (PMID 30626116, 2019).
Dengue virus infection (6 papers, 2014 to 2023). "The p42 isotype of OAS1 used our studies has been previously implicated to combat Dengue virus infection via an RNase L dependent pathway." (PMID 24651762, 2014). "In addition, other members of the OAS gene family, as OAS1 p42, OAS1 p46, and OAS3 p100 have been shown to have antiviral effects in dengue complication." (PMID 26302899, 2015).
diabetes (6 papers, 2008 to 2025). "In the SNP associated with diabetes, the expression of the OAS1 isoform p46 prevails, and we have seen that this isoform is localized to the mitochondria." (PMID 25205466, 2014). "As Mx1, Ifit1, and Oas1 ISGs were increased in young mice, it seems probable that the increase in these ISGs contributed to diabetes onset." (PMID 38487540, 2024).
tuberculosis (6 papers, 2018 to 2025). A chronic, recurrent infection caused by the bacterium Mycobacterium tuberculosis. "For example, genetic studies have linked the same rs10774671-G (OAS1-P46) allele to protection against tuberculosis, implying that OAS1 function affects intracellular bacterial control." (PMID 41472304, 2025). "We investigated the association of polymorphisms in OAS1 with tuberculosis (TB)." (PMID 30497421, 2018). "The 2′,5′-oligoadenylate synthetase (OAS) family, including OAS1, OAS2, and OAS3, is composed of IFN-induced antiviral enzymes and has been well studied in the field of tuberculosis." (PMID 36567857, 2022). "In the current study, six genes (IFITM1, IRF9, MX1, OAS1, STAT1, and STAT2) of the “host response signature network” are significantly overlapping with the “human immune response to tuberculosis” pathway with p-value 1.57e-8." (PMID 33362771, 2020).
gastric cancer (5 papers, 2019 to 2025). A primary or metastatic malignant neoplasm involving the stomach. "In trastuzumab-resistant gastric cancer, OAS1, OAS2, OAS3, and OASL were all identified as key genes." (PMID 38380081, 2024). "For HER2+ gastric cancer, the high expression of VIM, IFI44, IFI44L, IFIT2, IFIT3, ISG15, OAS1, or OASL was associated with worse overall survival (P < 0.05)." (PMID 31949544, 2019). "OAS1, OAS2, OAS3, and OASL have been recognised as pivotal genes in a bioinformatic study focusing on trastuzumab-resistant gastric cancer." (PMID 36567857, 2022). "Our previous research indicated that OAS1, OAS2, OAS3 and OASL were all identified as hub genes from the protein-protein interaction network of differentially expressed genes between the trastuzumab-resistant gastric cancer and control groups." (PMID 32560641, 2020).